CELSR3 (cadherin EGF LAG seven-pass G-type receptor 3)
Description:
Receptor that may have an important role in cell/cell signaling during nervous system formation.
Synonyms: hFmi1; CDHF11; EGFL1; FMI1; MEGF2; ADGRC3; RESDA1
Tractability: Antibody: UniProt places it where antibodies can reach, with medium confidence; UniProt predicts a signal peptide or a membrane-spanning region; its Gene Ontology location is reachable by antibodies, with medium confidence. PROTAC: ubiquitination databases record sites on it; its protein half-life has been measured.
Gene: Protein-coding gene on chromosome 3 (48,636,463 to 48,662,886, reverse strand). Ensembl gene ENSG00000008300.
Subcellular location: Cell membrane
Gene Ontology:
Molecular function: protein binding; G protein-coupled receptor activity; calcium ion binding; transmembrane signaling receptor activity
Biological process: axonogenesis; cell-cell adhesion mediated by cadherin; dopaminergic neuron axon guidance; G protein-coupled receptor signaling pathway; serotonergic neuron axon guidance; Wnt signaling pathway, planar cell polarity pathway; cell adhesion; cell surface receptor signaling pathway; homophilic cell-cell adhesion; signal transduction
Cellular component: adherens junction; membrane; plasma membrane
Genetic constraint (gnomAD): Loss-of-function variants: 71 observed, 251.72 expected, observed/expected ratio (o/e) 0.28, 90% interval 0.23 to 0.34. The upper end of that interval is the gene's LOEUF score, 0.34, which puts it in group 1 of 6, group 1 being the genes least tolerant of losing a copy. Missense variants: 3,586 observed, 4,526 expected, observed/expected ratio (o/e) 0.79, 90% interval 0.77 to 0.81. Synonymous variants: 1,763 observed, 1,898.1 expected, observed/expected ratio (o/e) 0.93, 90% interval 0.89 to 0.97.
Homologues: Orthologues: chimpanzee CELSR3 (99% identical), macaque CELSR3 (98% identical), pig CELSR3 (94% identical), rabbit CELSR3 (93% identical), dog CELSR3 (93% identical), mouse Celsr3 (92% identical), rat Celsr3 (92% identical), guinea pig CELSR3 (91% identical), tropical clawed frog celsr3 (63% identical), zebrafish celsr3 (43% identical), Drosophila melanogaster stan (34% identical), Caenorhabditis elegans fmi-1 (22% identical), and 2 more. Paralogues in human: CELSR2 (46% identical), CELSR1 (44% identical), FAT1 (19% identical), FAT3 (19% identical), FAT4 (16% identical), FAT2 (16% identical).
Diseases named in the same sentence as CELSR3 in open-access papers:
CELSR3 is named in the same sentence as 60 diseases in open-access papers, as found by Europe PMC text mining. Sharing a sentence is not in itself a finding about the gene and the disease. The quoted sentences say what the papers report.
hepatocellular carcinoma (9 papers, 2019 to 2024). A malignant tumor that arises from hepatocytes. "All these findings demonstrate that CELSR3, GPSM2, and CHEK1 were upregulated in hepatocellular carcinoma and linked to prognosis of patients with hepatocellular carcinoma." (PMID 32257949, 2020). "However, CELSR3 has been reported to be highly expressed in hepatocellular carcinoma, prostate cancer, and lung adenocarcinoma and indicates a poor prognosis." (PMID 37106442, 2023). "CELSR3 mRNA expression is upregulated in hepatocellular carcinoma and indicates poor prognosis." (PMID 34364397, 2021). "Some studies, for example, found that CELSR3 was highly expressed in the early stages of cancer and remained present throughout the entire cancer process, implying that CELSR3 may play a key role in the carcinogenesis of hepatocellular carcinoma." (PMID 38507078, 2024). "Cadherin EGF LAG seven-pass G-type receptor 3 (CELSR3) has been reported in cancers but its role and potential molecular mechanism in hepatocellular carcinoma (HCC) is unclear." (PMID 32226501, 2020). "The results suggested that high expression of CELSR3, GPSM2, or CHEK1 indicated poor prognosis in patients with hepatocellular carcinoma." (PMID 32257949, 2020). "CELSR3, GPSM2, and CHEK1 expression were markedly higher in hepatocellular carcinoma than that in normal controls." (PMID 32257949, 2020). "Theoretically, miRNAs that potentially bind to oncogenic CELSR3, GPSM2, and CHEK1 should be downregulated in hepatocellular carcinoma and display favorable prognostic roles." (PMID 32257949, 2020). "Next, Oncomine database was further introduced to analyze CELSR3, GPSM2, and CHEK1 expression in hepatocellular carcinoma." (PMID 32257949, 2020). "All these findings indicate that high expression of CELSR3, GPSM2, or CHEK1 links to unfavorable prognosis of patients with hepatocellular carcinoma." (PMID 32257949, 2020). "Therefore, CELSR3, GPSM2 and CHEK1 were considered as three novel potential prognostic biomarkers for hepatocellular carcinoma." (PMID 32257949, 2020). "The rest three genes (CELSR3, GPSM2, and CHEK1) have not been studied for their prognostic values in hepatocellular carcinoma so far." (PMID 32257949, 2020).
prostate carcinoma (5 papers, 2021 to 2024). A carcinoma that arises from epithelial cells of the prostate gland. "CELSR3 gene expression has been linked to a poor prognosis in patients with primary prostate cancer but its expression in advanced CRPC and NEPC has yet to be determined." (PMID 37546702, 2023). "This expression pattern of CELSR3 can be used as a prognostic biomarker and is associated with poor prognosis in patients with prostate cancer." (PMID 33442409, 2021). "CELSR3 expression may serve as a prognostic biomarker in patients with prostate cancer and may predict poor outcomes." (PMID 36339718, 2022). "We also discovered CELSR3 to be overexpressed in NEPC compared with CRPC, prostate cancer, and benign tissue." (PMID 37546702, 2023). "CELSR3 was found to be overexpressed in NEPC compared with CRPC, prostate cancer, and benign tissue." (PMID 37546702, 2023). "However, the clinical significance of CELSR3 in prostate cancer (PCa) has not been fully studied." (PMID 33442409, 2021).
colorectal cancer (4 papers, 2021 to 2024). A primary or metastatic malignant neoplasm that affects the colon or rectum. "The authors showed that CELSR3 had a unique gene variant in metastatic patients, suggesting that CELSR3 was involved in the metastasis of colorectal cancer by altering the structure of the gene or its mutation." (PMID 33442409, 2021). "Evidence is accumulating that a human ortholog of Fmi, CELSR3, is expressed at high levels in a range of solid tumors, including lung, prostate, pancreatic, hepatic, ovarian, and colorectal cancers, and in some cases has been shown to be associated with poor prognosis." (PMID 39854621, 2024). "Several human cancers, including brain tumors, ovarian cancer, pancreatic cancer, liver cancer, colorectal cancer, and cervical cancer, have been shown to have overexpressed CELSR3 genes." (PMID 38507078, 2024). "According to reports, the CELSR3 gene is overexpressed in various human cancers, including brain tumors, ovarian cancer, pancreatic cancer, liver cancer, colorectal cancer and cervical cancer." (PMID 33442409, 2021).
pancreatic cancer (4 papers, 2010 to 2024). "While hepatocytes were mostly unstained some pancreatic acini and pancreatic cancer cells were also positive for CELSR3." (PMID 20416094, 2010). "The results showed that CELSR3 was highly expressed in stellate cells of pancreatic cancer and could be a selective target providing a favorable therapeutic strategy." (PMID 33442409, 2021). "Other novel FTSEC biomarkers that are overexpressed in HGSOCs include CELSR3, an atypical cadherin; ABCC3, an ABC transport protein implicated in drug resistance; and CTHRC1, a secreted protein shown to be a candidate biomarker for breast and pancreatic cancer." (PMID 24070420, 2013).
brain tumors (3 papers, 2019 to 2024). "Recently, a relationship between CELSR3 expression and tumors, such as adult brain tumor and ovarian cancer, has also been reported." (PMID 31608178, 2019). "Recent studies have shown that CELSR3 expression in adult brain tumors reflects the role of CELSR3 in carcinogenic processes." (PMID 31608178, 2019).
liver cancer (3 papers, 2019 to 2024). An epithelial or non-epithelial malignant neoplasm that arises from the liver. "Correlation between the clinicopathologic variables and CELSR3 mRNA expression in liver cancer." (PMID 31608178, 2019). "These four pathways may be important biological pathways for the involvement of CELSR3 mRNA in the pathogenesis of liver cancer and deserve further in-depth investigation." (PMID 31608178, 2019). "Notably, these data suggested that these pathways might be key pathways for CELSR3 regulation of liver cancer." (PMID 33442409, 2021). "In addition, G1 pathway, ATRBRCA pathway, E2F targets, G2 M checkpoint and spermatogenesis may be the key pathways through which CELSR3 regulates liver cancer." (PMID 31608178, 2019). "GO somatic diversification of immune receptors, GO endonuclease activity, GO DNA repair complex and GO somatic cell DNA recombination may be important biological pathways through which CELSR3 mRNA participates in the pathogenesis of liver cancer, which deserve further study." (PMID 31608178, 2019).
lung adenocarcinoma (3 papers, 2021 to 2023). A carcinoma that arises from the lung and is characterized by the presence of malignant glandular epithelial cells. "Low expression of CELSR3 significantly reduces the migration and invasion of lung adenocarcinoma cells." (PMID 36339718, 2022).
lung carcinoma (3 papers, 2021 to 2024). "Previous reports indicate that miR-1-3p has an inhibitory role in lung cancer by targeting CELSR3 and FAM83A and modulating the viability, migration, and invasion of tumor cells." (PMID 38261568, 2024). "We performed knockdown of CELSR3 in the lung cancer cell lines A549 and H1975." (PMID 33811453, 2021).
oral squamous cell carcinoma (3 papers, 2019 to 2023). "This is consistent with previous findings that have implicated CELSR3 in axonogenesis, neuron migration, and cell-cell adhesion in oral squamous cell carcinoma cells as well as in neuroblast migration in the postnatal brain." (PMID 37546702, 2023). "CELSR3 has previously been implicated in axonogenesis, neuron migration, and cell-cell adhesion, all of which are involved in the process of perineural invasion in oral squamous cell carcinoma and neuroblast migration in postnatal brain." (PMID 37546702, 2023). "Meanwhile module analysis for the PPI network (down regulated), methylation inactivation of tumor suppressor gene CELSR3 was identified with the development of oral squamous cell carcinoma, but loss of this gene may be responsible for the pathogenesis of GBM." (PMID 31137733, 2019). "CELSR3 is hypermethylated in oral squamous cell carcinoma (OSCC) and can be used as a potential biomarker for the diagnosis, prognosis, and treatment of OSCC." (PMID 31608178, 2019).
Tourette syndrome (3 papers, 2017 to 2025). A neurologic disorder caused by defective metabolism of the neurotransmitters in the brain. "CELSR3 variants have been occasionally detected in various neurological diseases, including autism spectrum disorder, developmental delay, epileptic encephalopathy, intellectual disability, neural tube defects, and Tourette syndrome." (PMID 34951123, 2022).
craniorachischisis (2 papers, 2018 to 2023). Craniorachischisis is the most severe form of neural tube defect in which both the brain and spinal cord remain open to varying degrees. "For instance, variants in the CYP26B1 gene, occurring concurrently with other variants in neural tube-related genes such as CELSR3 and REST, were hypothesized to be associated with the craniorachischisis phenotype." (PMID 37424722, 2023).
epilepsy (2 papers, 2022 to 2023). A brain disorder characterized by episodes of abnormally increased neuronal discharge resulting in transient episodes of sensory or motor neurological dysfunction, or psychic dysfunction. "The phenotypical spectrum of CELSR3 variants potentially ranges from mild FS and/or epilepsy to neurodevelopmental disorders or even early death, depending on the dose of gene damage, which warrants further verification." (PMID 34951123, 2022). "Five heterozygous missense variants in CELSR3 are detected in five unrelated cases from a cohort of patients with febrile seizures (FS)/epilepsy with antecedent FS (EFS+) by performing trios‐based whole‐exome sequencing." (PMID 34951123, 2022). "The present study focused on epilepsy, which is potentially one of the phenotypes within the spectrum of CELSR3 variants." (PMID 34951123, 2022). "Trio-based WES has been successful in defining the most likely epilepsy-implicated loci and screening out candidate genes, such as UNC13B, CELSR3, and CDK19 in numerous studies." (PMID 37152436, 2023).
neural tube defect (2 papers, 2022 to 2025). A congenital defect characterized by failure of the neural tube to close completely; this results in the presence of openings in the brain or spinal cord. "Second, CELSR3 variants are potentially associated with other neurodevelopmental disorders, such as neural tube defects, developmental delay/intellectual disability, and autism spectrum disorders." (PMID 34951123, 2022).
small intestinal neuroendocrine tumors (2 papers, 2019 to 2023). "CELSR3 has been shown to regulate neural precursor cell fate decisions through the Wnt signaling pathway and has been previously identified in small intestinal neuroendocrine tumors." (PMID 37546702, 2023).
benign prostatic hyperplasia (1 paper, 2021). A non-cancerous nodular enlargement of the prostate gland. "We confirmed that CELSR3 was significantly upregulated in PCa (primary PCa and metastatic castration-resistant prostate cancer) when compared to benign prostatic hyperplasia in the PCTA dataset (P<0.001)." (PMID 33442409, 2021).
Encephalocele (1 paper, 2018). A neural tube defect characterized by sac-like protrusions of the brain and the membranes that cover it through openings in the skull. "Case NTD_122 with CELSR2 p.Arg1990His and CELSR3 p.Argy1194His had encephalocele." (PMID 29618362, 2018).
Epileptic encephalopathy (1 paper, 2022). A condition in which epileptiform abnormalities are believed to contribute to the progressive disturbance in cerebral function. "Therefore, the association between homozygous CELSR3 variants and epileptic encephalopathy was uncertain." (PMID 34951123, 2022).
Fanconi anemia (1 paper, 2024). Fanconi anemia (FA) is a hereditary DNA repair disorder characterized by progressive pancytopenia with bone marrow failure, variable congenital malformations and predisposition to develop hematological or solid tumors. "KEGG pathway analysis demonstrated that these genes related to CELSR3 were mainly enriched in signal pathways such as Fanconi anemia pathway, Propanoate metabolism, Carbohydrate digestion and absorption, Taurine and hypotaurine metabolism." (PMID 38507078, 2024).
Hydrocephalus (1 paper, 2016). Hydrocephalus is an active distension of the ventricular system of the brain resulting from inadequate passage of CSF from its point of production within the cerebral ventricles to its point of absorption into the systemic circulation. "Mice missing the PCP genes Celsr2 and Celsr3 develop hydrocephalus linked to defective motile cilia." (PMID 27055101, 2016).
infantile epileptic encephalopathy (1 paper, 2022). an epileptic condition characterized by epileptiform abnormalities associated with progressive cerebral dysfunction. "In previous studies, three homozygous CELSR3 variants were reported, including two homozygous CELSR3 variants (c.6407G>A/p.Gly2136Asp21 and c.7890G>A/p.Met2630Ile20) identified in patients with early infantile epileptic encephalopathy." (PMID 34951123, 2022).
Intellectual disability (1 paper, 2022). "A homozygous CELSR3 variant was identified in a case with intellectual disability." (PMID 34951123, 2022).
liver cirrhosis (1 paper, 2019). "It is worth noting that the expression of CELSR3 mRNA in liver cirrhosis tissues was lower than in normal and HCC tissues." (PMID 31608178, 2019).
migraine (1 paper, 2025). "Genes shared between Overall migraine and MA included RERG (PoPS Score Overall: 0.50, MA: 0.94), associated with neuroinflammatory pathways, and CELSR3 (PoPS Score Overall: 0.12, MA: 0.09), involved in planar cell polarity." (PMID 40826382, 2025).
oral cancers (1 paper, 2022). "In addition, CELSR3 is highly expressed in liver and oral cancers and associated with a poor prognosis." (PMID 36339718, 2022).
pancreatitis (1 paper, 2011). Inflammation of the pancreas. "Expression of stellate cell markers CELSR3, PBX1 and GFAP was observed in BMD cancer-associated PaSCs, however cancer-associated, but not pancreatitis-associated BMD PaSCs, expressed the cancer PaSC specific marker CELSR3." (PMID 22022519, 2011).